HSP90AB3P (heat shock protein 90 alpha family class B member 3, pseudogene)
Description:
Putative molecular chaperone that may promote the maturation, structural maintenance and proper regulation of specific target proteins.
Synonyms: HSP90BC; HSPCP1
Gene: Processed pseudogene on chromosome 4 (87,891,843 to 87,894,015, forward strand). Ensembl gene ENSG00000183199.
Subcellular location: Cytoplasm
Diseases named in the same sentence as HSP90AB3P in open-access papers:
HSP90AB3P is named in the same sentence as 2 diseases in open-access papers, as found by Europe PMC text mining. Sharing a sentence is not in itself a finding about the gene and the disease.
HSP90AB3P shares sentences with these, for which no sentence is quoted: cancer (1 paper); tumor (1).